SIT1 (signaling threshold regulating transmembrane adaptor 1)
Description:
Negatively regulates TCR (T-cell antigen receptor)-mediated signaling in T-cells. Involved in positive selection of T-cells.
Synonyms: SIT; SIT-R
Tractability: Antibody: UniProt places it where antibodies can reach, with high confidence; its Gene Ontology location is reachable by antibodies, with high confidence; UniProt predicts a signal peptide or a membrane-spanning region. PROTAC: ubiquitination databases record sites on it; its protein half-life has been measured.
Gene: Protein-coding gene on chromosome 9 (35,649,288 to 35,650,963, reverse strand). Ensembl gene ENSG00000137078.
Subcellular location: Cell membrane
Gene Ontology:
Molecular function: kinase binding; protein binding; SH2 domain binding
Biological process: regulation of T cell activation; signal transduction; T cell homeostasis
Cellular component: extracellular exosome; plasma membrane
Genetic constraint (gnomAD): Loss-of-function variants: 19 observed, 22.49 expected, observed/expected ratio (o/e) 0.84, 90% interval 0.59 to 1.24. The upper end of that interval is the gene's LOEUF score, 1.24, which puts it in group 5 of 6, group 1 being the genes least tolerant of losing a copy. Missense variants: 213 observed, 241.79 expected, observed/expected ratio (o/e) 0.88, 90% interval 0.79 to 0.99. Synonymous variants: 114 observed, 101.66 expected, observed/expected ratio (o/e) 1.12, 90% interval 0.96 to 1.31.
Homologues: Orthologues: chimpanzee SIT1 (100% identical), macaque SIT1 (96% identical), pig SIT1 (78% identical), dog SIT1 (75% identical), rabbit SIT1 (71% identical), rat Sit1 (71% identical), mouse Sit1 (70% identical), guinea pig SIT1 (69% identical).
Diseases named in the same sentence as SIT1 in open-access papers:
SIT1 is named in the same sentence as 32 diseases in open-access papers, as found by Europe PMC text mining. Sharing a sentence is not in itself a finding about the gene and the disease. The quoted sentences say what the papers report.
COVID-19 (6 papers, 2020 to 2024). A disease caused by infection with severe acute respiratory syndrome coronavirus 2. "Genetic deficiency of SIT1 leads to iminoaciduria in mice and gains importance in humans in the context of severe COVID-19 complications (discussed in Section 6)." (PMID 33142989, 2020). "A significantly higher frequency of the risk allele for severe COVID-19 was found on chromosome 3, which codes for the SIT1 amino acid transporter as well as receptors for inflammatory cytokines, CC-motif chemokine receptor 9 (CCR9) and the C-X-C motif chemokine receptor 6 (CXCR6) among other genes." (PMID 33142989, 2020). "To understand the structural basis of proline import, we solved the structure of the proline transporter SIT1 in complex with the COVID-19 viral receptor ACE2 by cryo-electron microscopy." (PMID 38951531, 2024). "It is unclear how dimeric and/or monomeric forms of ACE2 influence the activity of B0AT1 and SIT1/SGLT1 in response to the binding of one or two SARS-CoV-2 particles in patients with COVID-19." (PMID 33142989, 2020). "The main urine amino acids during COVID-19 include neutral amino acids (e.g., phenylalanine, leucine, tryptophan) and imino acids (e.g., proline), which are transported by B0AT1/SLC6A19 and SIT1/SLC6A20, respectively." (PMID 35705608, 2022).
breast cancer (4 papers, 2013 to 2022). A primary or metastatic malignant neoplasm involving the breast. "Novel GRB2-interactions (CNAIP and SIT1) with phosphotyrosine located at the ITAM region are critical for activating cytokine promoters as well as viral virus induced mammary tumors." (PMID 23826330, 2013). "Another report revealed that hypermethylation of genes (LAX1, SIT1, and UBASH3A) leads to enhanced anti-tumor T-cell responses in breast cancer." (PMID 35517856, 2022).
Aminoaciduria (2 papers, 2015 to 2025). An increased concentration of an amino acid in the urine. "The review highlighted 9 genes associated with aminoacidurias, including SLC3A1 (rBAT), SLC7A9 (bo,+AT), SLC6A19 (BoAT1), SLC7A7 (y+LAT1), SLC7A6 (y+LAT2), SLC36A2 (PAT-2), SLC6A20 (SIT-1), SLC6A18 (BoAT3), and SLC1A1 (EAAT3)." (PMID 41142409, 2025). "Collectrin-null mice show reduced amounts of several AATers, including B0AT1 and SIT1, at the brush border membrane of renal PT cells and severe aminoaciduria." (PMID 26361046, 2015).
diabetes (2 papers, 2011 to 2021). "In 10/71 (14%) of the patients, accompanying pathology was identified: 6 (8.4%) were severely malnourished, 2 (2.8%) had a coinfection with human immunodeficiency virus, 1 (1.4%) patient harboring a SIT1/Beijing genotype had diabetes mellitus, and 1 (1.4%) presented with alcoholism." (PMID 22567263, 2011).
iron deficiency (2 papers, 2013 to 2025). "Although the present data could not sort out direct and indirect iron-regualtory events, these results at least partially suggested that C. albicans Aft2 has an effect on the expression of FRP1 and SIT1 under alkaline environment and iron deficiency." (PMID 23626810, 2013).
metastatic tumors (2 papers, 2020 to 2022). "For skin cutaneous melanoma (SKCM), SIT1 mRNA was much higher in metastatic tumors than in primary tumors, however, there was no comparison of data for SIT1 expression in SKCM tissues and adjacent normal tissues because of a very small normal tissue sample size in the dataset." (PMID 36675674, 2022).
viral infection (2 papers, 2021 to 2023). "Although these ACE2:SIT1 or ACE2: B0AT1 heterodimers have been proposed to function as binding sites for the SARS‐CoV‐2 spike proteins, there is really no clear evidence that this association affects the role of ACE2 in viral infection." (PMID 34755492, 2021).
aspergillosis (1 paper, 2021). Aspergillosis is an infection, growth, or allergic response caused by the Aspergillus fungus. "The genes encoding Sit1 and Sit2 are expressed during infection as shown in a murine aspergillosis model, which is expected because all available data indicate that all iron acquisition systems are coregulated including SITs for both endogenous siderophores and xenosiderophores." (PMID 34575806, 2021). "Nevertheless, VL-2397, which is imported exclusively by Sit1, displayed antifungal activity with high efficacy in vitro and in vivo in a murine aspergillosis model." (PMID 34575806, 2021).
cholangiocarcinoma (1 paper, 2022). A carcinoma that arises from the intrahepatic biliary tree (intrahepatic cholangiocarcinoma) or from the junction, or adjacent to the junction, of the right and left hepatic ducts (hilar cholangiocarcinoma). "SIT1 expression was higher compared to adjacent normal tissues in cholangiocarcinoma, lung adenocarcinoma, esophageal carcinoma, liver hepatocellular carcinoma, head and neck squamous cell, kidney renal papillary cell carcinoma, and kidney renal clear cell carcinoma." (PMID 36675674, 2022).
colon adenocarcinoma (1 paper, 2022). "On the contrary, SIT1 expression was lower in tumor tissues than normal tissues in colon adenocarcinoma, kidney chromophobe, lung squamous cell carcinoma, rectum adenocarcinoma, and thyroid carcinoma." (PMID 36675674, 2022).
colorectal cancer (1 paper, 2022). A primary or metastatic malignant neoplasm that affects the colon or rectum. "In contrast, SIT1 expression in cervical and colorectal cancers was lower compared to the normal tissues in some datasets." (PMID 36675674, 2022).
cryptococcosis (1 paper, 2024). An acute or chronic, localized or disseminated infection by Cryptococcus neoformans. "However, the mutants lacking SIT1 still caused the wild-type level of virulence in a murine model of cryptococcosis suggesting that SIT1 was dispensable for disease." (PMID 38881181, 2024).
gastric cancer (1 paper, 2022). A primary or metastatic malignant neoplasm involving the stomach. "The SIT1 expression levels in breast and gastric cancers were higher than in the adjacent normal tissues." (PMID 36675674, 2022).
head and neck squamous cell carcinoma (1 paper, 2022). A squamous cell carcinoma that arises from any of the following anatomic sites: lip and oral cavity, nasal cavity, paranasal sinuses, pharynx, larynx, and salivary glands. "In addition, the immune cell infiltration levels varied between different SIT1 gene copy numbers in head and neck squamous cell carcinoma, lung squamous cell carcinoma, stomach adenocarcinoma, and SKCM." (PMID 36675674, 2022).
iminoglycinuria (1 paper, 2024). A metabolic disorder resulting from defective renal tube reabsorption of proline, hydroxyproline and glycine. "By comparing apo and substrate-bound SIT1 states, we also identify the structural changes that link substrate release and opening of the cytoplasmic gate and provide an explanation for how a missense mutation in the transporter causes iminoglycinuria." (PMID 38951531, 2024).
melanoma (1 paper, 2022). A malignant, usually aggressive tumor composed of atypical, neoplastic melanocytes. "It is possible that a few melanoma cells express SIT1 protein and release it into the tumor microenvironment by exosome to regulate tumor immune response." (PMID 36675674, 2022). "However, a lower SIT1 protein expression was also found in the plasma of a very small percentage of melanoma cells using the immunohistochemistry method through the Protein Atlas website." (PMID 36675674, 2022). "Based on SIT1-associated immunomodulators, we built a 13-gene signature by LASSO Cox regression which served as an independent prognostic factor for the survival of melanoma patients." (PMID 36675674, 2022). "Thus, the biological function of SIT1 in melanoma immunity is complicated; it would be very important and interesting to focus on the subject in the future." (PMID 36675674, 2022).
Neonatal sepsis (1 paper, 2021). Systemic inflammatory response to infection in newborn babies. "Interestingly, we found that the promoters of genes involved in T-cell regulation (i.e., CD3D, CD3G, UBASH3A, SIT1, and TXK) were hypermethylated in neonatal sepsis compared to controls, thereby resulting in decreased expression." (PMID 33659006, 2021).
skin cutaneous melanoma (1 paper, 2022). "However, the relationship between SIT1 and the prognosis of skin cutaneous melanoma (SKCM) and tumor-infiltrating lymphocytes remains elusive." (PMID 36675674, 2022).
infection (7 papers, 2011 to 2024). The state of being infected such as from the introduction of a foreign agent such as serum, vaccine, antigenic substance or organism. "Indeed, we found that genes activated throughout the prompt response of C. glabrata upon infection (24 h and 48 h) were enriched for gene ontology (GO) terms associated with iron ion transport (P = 6.05 × 10−6), including SIT1 and FTR1." (PMID 39475321, 2024). "The siderophore-iron transporter Sit1 and the high-affinity iron permease Ftr1 have been reported to be required for Fe acquisition and survival of C. glabrata during macrophage infection (35, –, 37)." (PMID 39475321, 2024). "The up-regulation of SIT1 and related genes (B9J08_001519, B9J08_001548, B9J08_001547) during blood infection highlights the relevance of these processes for C. auris in an environment which is virtually free of unbound iron ions." (PMID 35142597, 2022). "The high transcript levels of sit1 early in infection confirm the iron-limited environment of the murine lung." (PMID 25375670, 2014). "In infection assays using both mouse and human macrophage cell lines we observe a strong Sit1-mediated, siderophore-dependent increase in C. glabrata survival that is blunted with increased macrophage Fe levels." (PMID 21445236, 2011). "A mutual interaction between ACE2 and SIT1 may thus affect infection capacity." (PMID 39159813, 2024). "The upregulation of SIT1, FTR1, and FET3 at 24 h post-invasive infection was then confirmed by qRT-PCR." (PMID 39475321, 2024). "Moreover, during infection in the presence of albumin, C. glabrata drastically changed the expression of genes involved in iron uptake (FTR1 and SIT1), intracellular iron distribution and consumption (FTH1, HMX1) and virulence (EPA1, YPS2, AUS1)." (PMID 34710198, 2021). "Consistent with this, infection of primary macrophages derived from a mouse model of Ferroportin disease in which macrophage Fe levels are chronically elevated demonstrated enhanced C. glabrata survival that is independent of Sit1-mediated siderophore utilization." (PMID 21445236, 2011).
tumor (3 papers, 2020 to 2022). "The RNA-seq data of TCGA_SKCM tumor samples were separated into SIT1high and SIT1low groups by the medium SIT1 mRNA level." (PMID 36675674, 2022). "Our findings provided evidence for SIT1’s implication in tumor immunity and survival of SKCM patients." (PMID 36675674, 2022). "Since the TCGA dataset did not contain a sufficient number of adjacent normal skin tissues, to further evaluate the difference in SIT1 mRNA expression between the tumor and adjacent normal tissues, we analyzed the difference in SIT1 mRNA expression in the GSE98394 dataset." (PMID 36675674, 2022). "Since SIT1 mRNA expression levels are negatively correlated to tumor purity in many types of cancers in our analysis and its protein is mainly expressed in T- and B-lymphocytes, a relatively higher SIT1 mRNA expression in tumor microenvironments represent a high degree of lymphocytes infiltration." (PMID 36675674, 2022). "Our research provides evidence that SIT1 may regulate SKCM tumor immune microenvironments." (PMID 36675674, 2022). "Thus, SIT1 may regulate tumor-specific cytotoxicity in SKCM." (PMID 36675674, 2022). "TIMER analysis revealed that KLRB1, SIT1, and GZMM were negatively correlated with tumor purity and positively correlated with the infiltration of B cells, neutrophils, macrophages, CD4 T cells, CD8 T cells, and dendritic cells." (PMID 33164640, 2020). "We found that KLRB1, SIT1, and GZMM were negatively correlated with tumor purity and positively correlated with the infiltration of B cells, CD4 T cells, CD8 T cells, neutrophils, macrophages, and dendritic cells." (PMID 33164640, 2020). "At last, the complicated molecular mechanisms of SIT1-medicated tumor immunity have not been addressed in this study." (PMID 36675674, 2022).
cancer (1 paper, 2022). A tumor composed of atypical neoplastic, often pleomorphic cells that invade other tissues. "The results showed that SIT1 mRNA expression levels were positively correlated to various types of immune cells in many types of cancers." (PMID 36675674, 2022). "Our results also demonstrate that SIT1 mRNA expression levels were positively correlated to various types of immune cells in many types of cancers, including SKCM." (PMID 36675674, 2022). "In addition, there are few studies showing the relationship between SIT1 and cancer biology or immunity." (PMID 36675674, 2022). "Since SKCM has shown a good response to cancer immunotherapy and the immune implication of the SIT1 gene in SKCM remains mostly unknown so far, we systematically elucidate the association between SIT1 and SKCM immunity as well as the SIT1-mediated immune response-associated signaling pathways." (PMID 36675674, 2022). "The immunity implications of the SIT1 gene in malignant tumors remain mostly unknown." (PMID 36675674, 2022).
SIT1 also shares sentences with these, for which no sentence is quoted: alcoholism (1 paper); candidiasis (1); esophageal carcinoma (1); fungal infections (1); iron (1); lung adenocarcinoma (1); lung squamous cell carcinoma (1); rectum adenocarcinoma (1); stomach adenocarcinoma (1); thyroid carcinoma (1); type 2 diabetes (1).